RNU1-33P (RNA, U1 small nuclear 33, pseudogene)
Gene: Small nuclear RNA gene on chromosome 6 (145,463,238 to 145,463,399, reverse strand). Ensembl gene ENSG00000201119.
Homologues: Orthologues: chimpanzee U1 (99% identical), macaque U1 (95% identical), macaque U1 (94% identical), macaque U1 (93% identical), dog U1 (72% identical), guinea pig U1 (70% identical), rat U1 (62% identical). Paralogues in human: RNU1-1 (81% identical), RNU1-2 (81% identical), RNU1-27P (81% identical), RNU1-28P (81% identical), RNU1-3 (81% identical), RNU1-4 (81% identical), RNVU1-18 (81% identical), RNVU1-29 (81% identical), U1 (81% identical), RNU1-89P (81% identical), RNVU1-28 (81% identical), RNVU1-7 (81% identical), and 133 more.